MMP10 (matrix metallopeptidase 10)
Diseases named in the same sentence as MMP10 in open-access papers (continued):
Sharing a sentence is not in itself a finding about the gene and the disease.
laryngeal carcinoma (1 paper, 2020). Carcinoma that arises from the laryngeal epithelium. "The green module was mapped on the HQ PPI network, and finally, the potential critical targets MMP1, MMP3, and MMP10 for the treatment of laryngeal cancer were obtained." (PMID 32636440, 2020). "In this study, we analyzed the gene expression data of 109 laryngeal cancer samples and screened to obtain three important targets (MMP1, MMP3, and MMP10)." (PMID 32636440, 2020).
leiomyoma (1 paper, 2021). A well-circumscribed benign smooth muscle neoplasm characterized by the presence of spindle cells with cigar-shaped nuclei, interlacing fascicles, and a whorled pattern. "Seven women with leiomyomas were evaluated, and MMP3 and MMP10 levels were measured." (PMID 33503183, 2021).
lupus nephritis (1 paper, 2025). Glomerulonephritis in the context of systemic lupus erythematosus. "Of particular interest, MMP-10 is induced in all kidney fibrosis models tested, such as UUO, UIRI, FAN, db/db mice, and Ang II-infusion, as well as in human kidney biopsies from patients with various CKD, such as IgA nephrology, diabetic nephrology and lupus nephritis." (PMID 40382334, 2025).
medulloblastoma (1 paper, 2025). A malignant, invasive embryonal neoplasm arising from the cerebellum. "A previous study demonstrated that disruption of APC/C function using CARP-1 functional mimetics significantly downregulated MMP expression, specifically MMP-10, in medulloblastoma cells, supporting our rationale." (PMID 40136519, 2025).
meningioma (1 paper, 2024). A generally slow growing tumor attached to the dura mater. "Significant fold changes were found in MMP10, TIMP1, and TIMP4 in meningioma patients." (PMID 38474106, 2024).
metastatic cancer (1 paper, 2020). A carcinoma which has spread from the original site of growth to another anatomic site. "The expression levels of MMP7, MMP13, MMP10, miR-7109-5p and miR-34b in nonmetastatic cancer samples and metastatic cancer samples were measured by qRT-PCR." (PMID 31996191, 2020).
metastatic melanoma (1 paper, 2015). A melanoma that has spread from its primary site to another anatomic site. "Moreover they suggest that other MMPs (MMP7, MMP10, MMP11, and MMP13) might be implicated in CNS invasion by metastatic melanoma cells." (PMID 25692137, 2015).
Miscarriage (1 paper, 2025). A pregnancy that ends at a stage in which the fetus is incapable of surviving on its own, defined as the spontaneous loss of a fetus before the 22th week of pregnancy. "Further research on 17 core enriched genes expressed at the MFI indicated that CXCL11, MMP10, FOS, FOSB, LY96, and NCF2 may be closely related to miscarriage." (PMID 41232126, 2025).
nasopharyngeal carcinoma (1 paper, 2015). A carcinoma arising from the nasopharyngeal epithelium. "MMP-3, MMP-10 and MMP-12 have been shown to be up-regulated in hnRNP-K-overexpressing lung and nasopharyngeal cancer cells." (PMID 26713736, 2015).
Neonatal sepsis (1 paper, 2025). Systemic inflammatory response to infection in newborn babies. "Other chemokines, including MMP- 10, CCL20, and CXCL1, have also been studied in diagnosing NEC and differentiating it from neonatal sepsis." (PMID 40295408, 2025).
oral candidiasis (1 paper, 2022). Infection of the mucosal lining of the mouth with the fungus Candida albicans. "Also, the expression of MMP1, MMP10, COL5A2, SERPINB4, and CRABP2 was increased under both conditions, confirming that oral candidiasis may drive OSCC progression events in vivo." (PMID 35089096, 2022).
ovarian adenocarcinoma (1 paper, 2012). An adenocarcinoma that arises from the ovary. "Interestingly, CSCs appear to promote chemoresistance and a recent study revealed that Mmp10 is overexpressed in cisplatin-resistant compared to cisplatin-sensitive human ovarian adenocarcinoma cells." (PMID 22545096, 2012).
pneumonia (1 paper, 2024). An acute, acute and chronic, or chronic inflammation focally or diffusely affecting the lung parenchyma, caused by an infection in one or both of the lungs (by bacteria, viruses, fungi, or mycoplasma.). "Mmp10−/− mice are more susceptible to pneumonia than wild-type mice." (PMID 39437760, 2024).
psoriasis (1 paper, 2019). An autoimmune condition characterized by red, well-delineated plaques with silvery scales that are usually on the extensor surfaces and scalp. "Then, chitinase-3-like protein 1 (CHI3L1) and MMP10 distinguished psoriasis from psoriatic arthritis not undergoing systemic therapy and, in the presence of onychopathy, MMP8 levels were higher in psoriasis than in psoriatic arthritis." (PMID 31717649, 2019).
pterygium (1 paper, 2021). A wedge-shaped fibrovascular lesion arising from the bulbar conjunctiva and extending to the cornea. "MMP3 was the only MMP/TIMP gene upregulated in pterygium, and only modestly, while MMP2, MMP7, MMP10, and MMP25 were downregulated." (PMID 34769520, 2021).
renal fibrosis (1 paper, 2025). A final common manifestation of a wide variety of chronic kidney diseases characterized by glomerulosclerosis and tubulointerstitial fibrosis. "To generalize the findings of MMP-10 in promoting renal fibrosis, we administered MMP-10-specific shRNA or control shRNA to a UIRI-induced kidney fibrosis model, starting at 4 days after surgery." (PMID 40382334, 2025). "In summary, we show in this study that upregulation of MMP-10 is a common and coherent response in kidney tubular epithelial cells after injury, which drives the development and progression of renal fibrosis." (PMID 40382334, 2025).
respiratory infections (1 paper, 2025). "Given that respiratory infections are a major cause of COPD exacerbations, we determined whether having pathogenic bacteria in sputum cultures obtained during exacerbations influenced the serum concentrations of CTRC, OSM, and MMP-10." (PMID 40343765, 2025).
rhabdomyolysis (1 paper, 2021). Necrosis or disintegration of skeletal muscle often followed by myoglobinuria. "Consistently, renal expression of MMP-10 was significantly induced in mouse rhabdomyolysis-associated AKI induced by glycerol." (PMID 33436543, 2021).
schistosomiasis (1 paper, 2018). An infectious disease caused by parasitic trematodes of the genus Schistosoma that colonize human blood vessels and release eggs that can cause granulomatous reactions leading to acute (swimmer's itch or acute schistosomiasis syndrome) or chronic disease. "In line with this, Schistosomiasis-HIV patients in our cohort who did not develop Schisto-IRIS showed a significant decline in MMP-10 levels during ART." (PMID 30089120, 2018).
Serous Ovarian Carcinoma (1 paper, 2025). "The tested matrilysins MMP-7 and MMP-26 and stromelysin MMP-10 have the highest initial diagnostic potential in detecting High-Grade Serous Ovarian Carcinoma." (PMID 40565125, 2025). "Of the MMPs tested, MMP-7, MMP-26, and MMP-10 have the highest potential in diagnostics of serous ovarian cancer patients." (PMID 40565125, 2025).
Skin ulcer (1 paper, 2013). A discontinuity of the skin exhibiting complete loss of the epidermis and often portions of the dermis and even subcutaneous fat. "MMP10 is regulated in a spatiotemporal manner during wound healing, with strong expression at both day 1 and day 5 post-wounding and has been observed in macrophage-rich areas of the dermis in human skin ulcers." (PMID 23691065, 2013).
teratoma (1 paper, 2018). A non-seminomatous germ cell tumor characterized by the presence of various tissues which correspond to the different germinal layers (endoderm, mesoderm, and ectoderm). "In immature teratomas, reduced methylation of MMP10 significantly enriched in axonal guidance signaling pathway." (PMID 29933410, 2018).
toxoplasmosis (1 paper, 2014). A parasitic disease contracted by the ingestion or fetal transmission of toxoplasma gondii. "In a mouse model of toxoplasmosis, in addition to inflammatory monocytes and neutrophils, CD4+ and CD8+ T lymphocytes where also important source of MMP-8 and MMP-10." (PMID 25393535, 2014).
urolithiasis (1 paper, 2023). Stone(s) within the urinary tract. "For LASSO regression analysis, six variables, MMP1, MMP3, MMP9, MMP10, MMP27 and, MMP28, were screened as diagnostic markers for urolithiasis." (PMID 37006258, 2023). "Subsequently, we extracted DMMMPs and genes in urolithiasis-related modules for intersection and found MMP1, MMP3, MMP9, MMP12 were in the royalblue module and MMP10 were in the green module, suggesting all of DEMMPs might be implicated in RPs and urolithiasis." (PMID 37006258, 2023).
ZIKV infection (1 paper, 2019). "Increased MMP10 and MMP13 are further supporting the notion that ZIKV infection promotes inflammation and extracellular remodeling." (PMID 31249527, 2019).
tumor (136 papers, 2001 to 2025). "While several studies on MMP-2 and MMP-9 have been reported, there are only a few reports on MMP10 and tumor associations." (PMID 36908704, 2023). "MMPs can be divided six subfamilies, of which MMP1 and MMP13 are collagenases and MMP3 and MMP10 are stromelysins, which have long been associated with tumor invasion, metastasis and angiogenesis." (PMID 36824434, 2023). "In the present paper, the areas under the ROC curve were evaluated in order to determine the diagnostic utility of MMP-3 and MMP-10 used separately and in combination with the commonly used BC tumor marker (CA 15-3)." (PMID 33371324, 2020). "In fact, over-expression of MMP-10 has been previously been reported in patients suffering from oesophageal squamous cell carcinoma and associated with tumour size and poor survival." (PMID 33126685, 2020). "Many over-expressed genes in tumor-associated T cells were involved in tissue remodeling (e.g., Col1a1, Col4a1, Fn1, Lamc1, Mmp2, Mmp10, Timp3) and cell motility/adhesion (Rhoc, Itga1, Itgav)." (PMID 31477729, 2019). "Expression of MMP10 was reported to be associated with poor prognosis and its function was reported to have a role in tumor development." (PMID 27072580, 2016). "Experimentally, we showed that MMP-10 can regulate tumor cell migration and invasion, and endothelial cell tube formation, and that MMP-10 effects are associated with a resistance to apoptosis." (PMID 24885595, 2014). "Oncospheres exhibit enhanced tumor-initiating and metastatic activity when injected orthotopically into syngeneic mice, whereas Mmp10-deficient cultures show a severe defect in tumor initiation." (PMID 22545096, 2012). "Mmp10-deficient mice exhibit a block in Kras-and urethane-induced tumor formation, an effect that correlates with an inability of Mmp10-deficient BASCs to expand and undergo transformation in response to urethane or Kras." (PMID 22545096, 2012). "Our results also demonstrate that MMP10 is highly expressed in many human tumor types, and is associated with poor outcome, metastatic potential and cancer stem cell signatures." (PMID 22022614, 2011). "More importantly, the tumor inhibitory effects of the genetic loss of Mmp10 are reflected in a defect in oncogenic expansion of BASCs in vivo and in vitro." (PMID 22022614, 2011). "MMP-10, also known as stromelysin, is a tumour-associated gene." (PMID 33173129, 2020). "Interestingly, Mmp10 knockdown in parental cells also leads to a loss of tumor formation in vivo, indicating that Mmp10 is important for the tumor-initiating activity of a CSC-like cell population present in parental cell cultures." (PMID 22545096, 2012). "Thus, while many Mmps produced by tumor-associated stroma play prominent roles in the invasive and metastatic properties of lung tumor cells, Mmp10 is produced primarily by lung tumor cells to support the autonomous growth of CSCs." (PMID 22545096, 2012). "Thus, the expression of MMP-10 was associated with the upregulation of key angiogenic and metastatic proteins in HeLa cells, factors which could facilitate tumor growth and progression." (PMID 24885595, 2014). "In this work, we present a continuation of the evaluation of matrilysins (MMP-7 and MMP-26) and stromelysins (MMP-3 and MMP-10) as novel tumor markers for women’s diseases —this time, as screening biomarkers of EC." (PMID 40332487, 2025). "MMPs are well-known factors associated with the tumour microenvironment (TME); MMP-2 and MMP-10 were identified as diagnostic indicators for PDAC and its progression in several studies." (PMID 37903909, 2024). "MMPs, including MMP-1 and MMP-10, known for their roles in esophageal tumorigenesis, were also found to be upregulated in tumor samples." (PMID 39123475, 2024). "Accordingly, in vivo siRNA therapeutics targeting MMP-10 have demonstrated a reduction in tumour growth and angiogenesis." (PMID 38032961, 2023).
tumor (continued). "Of note, an increased expression of MMP10 at the invasive fronts of the tumor was observed compared to the center of the tumor." (PMID 36650344, 2023). "MMP-10 is expressed by tumor cells in cSCC and it has been shown to contribute to cSCC progression by activating latent MMP-1 and MMP-13." (PMID 37864034, 2023). "Although MMP10 is primarily known for promoting metastatic potential of the tumor cells, literature also suggests a role of MMP10 in tumor initiation and progression." (PMID 36650344, 2023). "This study demonstrates that overexpression of MMP10 is sufficient and essential to induce tumor growth and nodal metastasis in an orthotopic mouse model." (PMID 36650344, 2023). "In agreement with the tumor suppressor role of miR-410 in LNCaP cells, a decrease in MMP10 expression was observed." (PMID 38201476, 2023). "FOXC1 downstream targets, such as MYC, LINC01123, and MMP10, have been reported to regulate tumor progression in various cancer types." (PMID 35406487, 2022). "SPINK1, FABP4, and MMP10 showed darker staining in tumor tissues, and GPRASP1, CLCA4, and LAMP5 showed lighter staining." (PMID 35479956, 2022). "Numerous studies show that knockdown of MMP-10 expression or blocking MMP-10 activity significantly reduces tumor cell invasion in vitro." (PMID 35216251, 2022). "Multivariate analysis model reveals that MMP-10 expression is an independent factor of tumor invasion in RCC patients." (PMID 35216251, 2022). "For another interesting example, tumor-specific keratinocyte (TSK) clusters were identified with MMP10 as a marker by the first generation of ST at the tumor leading edges in patients with squamous cell carcinoma." (PMID 36389765, 2022). "In human 786-0 VHL null RCC cell lines, IL-1β-induced RCC tumor cell invasion is, at least partially, dependent on MMP-10." (PMID 35216251, 2022). "Studies with NZB IL10 knockout mice evidence the IL10 role in B-1 cell expansion and development of CLL, whereas Mmp10 works by accelerating the tumor growth." (PMID 33659046, 2021). "Both G-CSF and MMP10 play an important role in cell migration and tumor progression properties of cancer." (PMID 34795329, 2021). "The present study showed the activity of MMP-3 and MMP-10 in both low-grade and high-grade tumor cells." (PMID 34441979, 2021). "It has been reported that Mmp10 and Mmp13 are highly expressed in tumor cells in cSCC37,38, and almost universally upregulated across all cancers by TCGA database analysis." (PMID 33664254, 2021). "In general, though, MMP1, MMP10 and PTHLH were mainly associated with poor prognosis, indicating a tumor promoting role in most cancers." (PMID 34301206, 2021). "Several studies have indicated an important role of MMP-3 and MMP-10 in the stimulation of tumor growth, metastasis, and angiogenesis in BC." (PMID 33371324, 2020). "Among them, the expressions of MMP1, MMP3, and MMP10 in tumor tissues were higher than those in normal tissues (p < 0.05)." (PMID 32636440, 2020). "Consistent with the results in the TCGA cohort, the mRNA expression of CSE1L, CSTB, MMP10 was significantly up-regulated in HCC while GYS2 was significantly down-regulated when compared with non-tumor tissues." (PMID 31139015, 2019). "We also confirmed by qPCR that a subset of these genes (Anxa10, Ctse, Mmp10, Mmp13, Lcp1) were consistently upregulated in shG9a tumor cells compared to controls." (PMID 30455465, 2018). "In vitro and in vivo studies revealed that G9a represses a gene signature highly associated with mutant KRAS-regulating and ECM-regulating genes, including Mmp10, which partially mediates the tumorigenicity of G9a-depleted tumor cells." (PMID 30455465, 2018). "In this study, the authors demonstrate that the histone methyltransferase G9a is a suppressor of lung tumor-propagating cells and tumor progression, acting through chromatin modification with MMP10 as one of its targets for metastasis regulation." (PMID 30455465, 2018).